NANOG (Nanog homeobox)
Diseases named in the same sentence as NANOG in open-access papers (continued):
Sharing a sentence is not in itself a finding about the gene and the disease.
tumor (continued). "In addition, key stemness markers, including NANOG, OCT4 and SOX2, were markedly upregulated in DUSP9‐overexpressing tumours, whereas their expression was significantly reduced in DUSP9‐knockdown tumours, further supporting the role of DUSP9 in promoting stemness." (PMID 41383134, 2025). "The levels of tumor stem-related proteins, including NANOG and Oct4, showed no significant changes." (PMID 39781469, 2025). "Furthermore, lower ZFP36 protein level and higher protein levels of LRP5, β-catenin, NANOG were observed in 5 tumor tissues rather than adjacent normal tissues." (PMID 40038255, 2025). "Additionally, SOX2 knockdown did not significantly affect the expression levels of OCT4 and NANOG, but markedly reduced the number of tumor spheres formed." (PMID 40821114, 2025). "Our results did not reveal a significant association between NANOG expression and survival in recurrent OSCC, suggesting its impact may be more relevant in tumor initiation or primary disease settings than at recurrence." (PMID 40227667, 2025). "In addition, it was demonstrated that changes in CD44 glycosylation regulate its binding to hyaluronic acid, fibronectin, collagen, and podoplanin, and modulates c-Src/STAT3/TWIST1, PI3K/AKT/mTOR, ERK/NF-kB/NANOG and other signaling pathways, modulating TME traits and tumor cells behavior." (PMID 39860065, 2025). "NANOG was highly expressed in the miR-135b-5p-high group within clusters 1 and 14, and elevated expression of C-MYC and CD24 was observed in the miR-135b-5p-high group within cluster 14, indicating a more remarkable stemness property of tumor cells in HCC with high miR-135b-5p expression." (PMID 36755690, 2023). "NANOG+ cells exhibited stem-like, metastatic, anti-apoptotic properties, and resistance to multi-modal therapies, such as chemo-, radio-, and immunotherapy, by hyperactivation of the EGFR-AKT pathway, indicating the important role of NANOG signaling in these refractory phenotypes of tumor cells." (PMID 37165076, 2023). "Furthermore, DSCC1 silence could downregulate the expression of multiple biomarkers of stem-like tumor cells, including SOX2, NANOG, and Oct-4." (PMID 37742009, 2023). "The knockdown of NANOG in the cisplatin-resistant tumor cells led to a significant decrease in autophagosome abundance, EGF secretion and the level of pEGFR, suggesting an important role of NANOG in regulating the autophagy-mediated EGFR activation of cisplatin-resistant tumor cells." (PMID 37165076, 2023). "Cluster 1 was characterized by upregulation of tumor-suppressing genes: HNF1B, CCNDBP1, PATJ, EPB41L3, MARVELD2, PTEN in conjunction with cell-cycle genes – GSPT1, GPR19, EAPP, KIT, CDKL1, and stem cell markers – RBBP5, NANOG, NCSTN, ERG, including quiescent stem cell markers—FOXP1, SMARCA2." (PMID 36348001, 2022). "Although the molecular markers that can be used to label tumor stem cell-like phenotypes were not very clear yet, SOX2, OCT4, and NANOG, which are transcription factors, have been confirmed to be the main regulatory factors to maintain tumor stem cell-like phenotypes." (PMID 32766132, 2020). "Moreover, this study uncovers a differential impact of NANOG and SOX2 expression on HNSCC prognosis, depending on tumor site and lymph node infiltration, which could facilitate high-risk patient stratification." (PMID 32635524, 2020). "Exploring the tumorigenic properties of OCT4, SOX2, and NANOG in HaCaT cell line, which did not form tumor in vivo, we found that it is possible to obtain tumorigenic cells from nontumorigenic cells, suggesting that they have CSC properties mediated by the presence of these transcriptional factors." (PMID 31885625, 2019). "We analyzed the significance among normal and tumor tissues, and we found that only OCT4 (p value < 0.0001) and SOX2 (p value = 0.0014) had higher expression in tumor tissues, not so for KLF4 (p value = 0.0610), C-MYC (p value = 0.0900), or NANOG (p value = 0.0969)." (PMID 31885625, 2019).
tumor (continued). "Analysis of H&E-stained sections revealed a comparable cellularity and overall morphology of the grafts to the surrounding mature host CNS tissue with no detectable tumor formation, supporting the absence of the NANOG-positive hESC contaminants in CoMo-NSC population as identified by RNA-seq." (PMID 30867054, 2019). "The OCT4-nuclear high/NANOG-nuclear high phenotype in RCC and ccRCC subtype indicated aggressive tumor behavior and predicted a worse clinical outcome, which may be a useful biomarker to identify patients at high risk of postoperative recurrence and metastasis." (PMID 30082842, 2018). "The increased expression of MK and NANOG was associated with histologically high-grade tumors (moderately- and poorly-differentiated OSCC) and clinically adverse prognosis (late tumor stage and lower overall survival rate), compared to tumors with weak or negative expression of MK and NANOG." (PMID 29113102, 2017). "As NANOG can be induced by HIF and cytokines including interleukin-6, tumor microenvironments such as hypoxia and inflammation may (epigenetically) reprogram non-CSCs to the CSC state through NANOG by similarly antagonizing/engaging lineage-specific TF signaling complexes." (PMID 27867534, 2016). "Interestingly, we observed heterogeneous expression of GLI1 and NANOG also within alveolar RMS patient tumor cores but without prognostic significance (data not shown)." (PMID 26189795, 2016). "4EGI-1 treated tumor cells presented decreased CSC pluripotency markers NANOG and OCT4, tumor metastasis regulator CXCR4, EMT mediator c-MYB and proangiogenic factor VEGF, but not translation initiation factors eIF1A or eIF5, comparing to vehicle treated breast CSC tumor cells in vivo." (PMID 25115391, 2014). "Besides the identification of tumor-initiating HCC cells, cancer-related molecules and signaling pathways, such as the polycomb group proteins, NANOG, AKT/PKB signal, and Wnt/β-catenin, have been shown to play an important role in maintaining or augmenting of tumor-initiating capability of TICs." (PMID 24454751, 2014). "In addition it could be demonstrated that inhibition of proliferation is associated with downregulation of the known stem cell factors NANOG, POU5F1 and SOX2 in tumor cells." (PMID 23969837, 2013). "In addition, overexpression of exogenous NANOG in HCT116 cells resulted in an increase of CD133+high population, suggesting that demethylation of NANOG promoter contributes to the initiation of CSCs in tumor development." (PMID 24023739, 2013). "C-MYC may function as an oncogene and OCT4, KLF4, NANOG and SOX2 as tumor suppressors." (PMID 21982273, 2011). "Given that we found the pluripotency factors NANOG, SOX2, and OCT4 as potential regulators of mesenchymal plasticity, we next aimed to investigate whether their expression predicts clinical variables that relate to therapy resistance and increased tumor cell mobility in EAC." (PMID 38760583, 2024). "Therefore, the lack of NANOG expression by MDA-MB-231 cells may have switched the oncogenic KLF4 to tumor suppressor mode, which consequently induced differentiation upon cisplatin and C. nutans treatment." (PMID 37250812, 2023). "However, how NANOG regulates tumor progression is still not known." (PMID 34638956, 2021). "According to the evidences herein presented, it is also plausible that these discrepancies could underscore the prominent role of NANOG expression in early stages of oral tumorigenesis as a tumor-initiating factor, rather than as a prognostic factor in advanced stages of the neoplastic disease." (PMID 31484317, 2019).
tumor (continued). "In addition, the expression patterns of MK and NANOG were correlated with the overall survival rate of OSCC patients, indicating that the IHC expression pattern of MK and NANOG in pretreatment biopsy specimens can be used as a tumor prognosis marker in these patients." (PMID 29113102, 2017). "Furthermore, over-expression of SOX2, OCT4 or NANOG alone is sufficient to enhance tumorigenesis in a mouse model; up-regulation of c-MYC has been reported to increase the CSC fraction by 150-fold, enabling tumor formation and serial propagation with as few as 500 cells." (PMID 26506421, 2016). "Thus, it is possible that specific tumor cells that did not express NANOG underwent cell death, while undifferentiated tumor cells, including CSCs overexpressing NANOG, survived and continued to proliferate in patients who underwent preoperative adjuvant therapy." (PMID 24348816, 2014). "Compared to tumors from mice that were not exposed to Paclitaxel treatment (primary tumor), tumors from recurrent disease after treatment with Paclitaxel (early recurrent tumor) had higher levels of genes associated with stemness such as ALDH1, KLF4, MYD88, NANOG, and OCT-4." (PMID 24403249, 2013). "In urethane-induced lung tumors, nuclear positivity of SOX2, OCT4, and NANOG was observed in some cells in both TC2N+/+ and TC2N-/+ tumor groups (red arrows), while no significant staining signal was observed in the TC2N-/- tumor group." (PMID 39849581, 2025). "For NANOG and ALDH1 inhibitors, such as Amcasertib and Disulfiram 48, 49, our preliminary data showed that their anti-tumor effect in HNSCC was not as good as MYCi975." (PMID 38169606, 2024). "To validate the antitumorigenic ability of HBIG or HCIG in vivo in NOG mice, we transplanted the NANOG+/CD133+/CD49f+cells with or without HBIG and determined the effect of PRI-724 on tumor growth." (PMID 37744383, 2023). "Cells with enhanced tumor-initiation capacity and resistance to chemotherapy in vitro have significantly enriched SOX2, but not OCT4 or NANOG." (PMID 33445692, 2021). "Overall, our results show that the expression of NANOG and ALDH1A3 remains stable during metastasis, probably not affected by change in the tumor microenvironment." (PMID 32423137, 2020). "We found that there is a difference in NANOG CNV in tumor samples compared to TANT; however, it seems that NANOG CNV has a certain role in its regulation but is not crucial for tumorigenesis." (PMID 32733958, 2020). "Although CD24 was excluded from the analysis since it was expressed by most tumor cells in our ascitic effusion samples, CD44+CD117+ cells significantly overexpressed NANOG, SOX2 and OCT4, compared with the negative counterpart CD44+CD117−." (PMID 28726781, 2017). "And although OCT4 and NANOG have demonstrated a positive correlation with tumour grade, the oncogenic role of OCT4 and NANOG and their importance in brain tumourigenesis has not been explored." (PMID 26580604, 2015). "Further analysis of the primary tumor by RT-PCR revealed the expression of the pluripotency markers POU5F1, NANOG and SOX2 in CD44+ but not CD44− subpopulations." (PMID 21124918, 2010). "Analysis based on the Spearman correlation coefficient indicated a very weak positive correlation between NSDHL and SOX2 expression in patient tumor tissues (n = 998, r = 0.089, P = 0.005), whereas a negative correlation was found between NSDHL and NANOG expression (n = 998, r = -0.038, P = 0.24)." (PMID 39516821, 2024). "Notably, we did not detect any human cells expressing pluripotency markers (NANOG and OCT4) or any signs of abnormal proliferation or tumour formation in the brains of any hiPSC-NSC-transplanted mice at 10-months post-transplantation." (PMID 39487141, 2024). "Also, tumor/nontumor (T/N) ratios of EFNA4, NANOG, OCT4, and EPHA10 mRNA expression had averages of 1.39, 1.25, 2.37, and 1.03, respectively." (PMID 33436772, 2021).
tumor (continued). "The mean number of CD20+ TILs in both the tumor and the surrounding stroma was consistently higher in tumors harboring negative expression of SOX2 and NANOG, although this inverse relationship only reached statistical significance for the SOX2 marker (p = 0.008)." (PMID 33494389, 2021). "Therefore, we concluded that D2 and NANOG are specifically expressed in the tumor epithelium of BCC and not in the CD34+ population of CSCs and that the expression of D2 and NANOG in CSCs drastically differs from that in the bulk of tumors." (PMID 32197405, 2020). "The expression of pluripotency markers, OCT3/4, NANOG, SOX2, and LIN28A, did not exhibit significant correlation with tumor formation latency and incidence, and the integration of reprogramming factor genes into genome of hiPSCs did not also affect the transcript expression." (PMID 30286143, 2018). "It is exciting to speculate that the CSC in MDBMSCC undergo EMT and preferentially express OCT4, pSTAT3, SOX2, and NANOG and potentially lose the expression of EMA and CD44, as none of these cells outside of the tumor nests express EMA or CD44." (PMID 27532037, 2016). "Indeed, all 3 populations were ALDH+ and formed serial spheroids but expressed different combinations of stem cell markers (CD133, CD105, CD146, CD29, OCT4, NANOG, and Nestin) and the non-CSC tumor marker E-cadherin." (PMID 27293448, 2016). "These cells, known as cancer stem cells (CSC) or tumor initiating cells, possibly originate from non-malignant stem cells or progenitor cells, with which they share several characteristics, including the expression of stem cell markers such as SOX2, NANOG, CD133, and CD44." (PMID 38303021, 2024). "A2BR knockdown did not affect tumor growth rate or sensitivity to paclitaxel, but attenuated paclitaxel-mediated increases of the percentage of ALDH+ cells, the number of mammosphere-forming cells, and the mRNA expression of pluripotency factors NANOG, SOX2, and KLF4." (PMID 35401817, 2022). "Here, we compared mRNA expression of NANOG and SOX2 between tumor cells co-cultured with or without CAFs and found decreased mRNA expression of SOX2 in tumor cells co-cultured with CAFs from LK1108, but in the other two cell lines, a tendency to increased expression of SOX2 and NANOG was found." (PMID 33353547, 2020).
infection (17 papers, 2011 to 2025). The state of being infected such as from the introduction of a foreign agent such as serum, vaccine, antigenic substance or organism. "Western blot results revealed that the expression of SIRT4, and a panel of stem cell-related molecules including ABCG2, BMI1, and NANOG was significantly suppressed in Hep-12 cells following infection with lentiviruses harboring SIRT4 shRNAs." (PMID 40384857, 2025). "A dramatic change in shape occurred in the fibroblast cells 7 days after infection and NANOG‐tdTomato‐positive colonies appeared at about 9 days post‐infection." (PMID 37190930, 2023). "Results showed that shRNA lentiviral infection of U-251 and U-373 cells efficiently reduced NANOG expression levels in both cell lines." (PMID 34638956, 2021). "Meanwhile, the H3K9me3 levels on the NANOG promoter significantly decreased under ETBF infection conditions and were restored after JMJD2B knockdown." (PMID 32684087, 2020). "To evaluate the induction of tumorigenicity in HaCaT cells by OSKM-N factors, we obtained cells that stably expressed OCT4, SOX2, KLF4, C-MYC, or NANOG by infection with lentiviral particles after the selection period." (PMID 31885625, 2019). "In order to determine whether the ability of RA and cDDP to down-regulate the expression of NANOG and POU5F1 is essential to their ability to acutely induce resistance to cDDP, NT2-D1 cells were molecularly engineered to constitutively express NANOG by infection with a retroviral expression vector." (PMID 24475288, 2014). "AAV8‐shNanog infection successfully suppressed NANOG expression as shown by non‐detection of hepatic Nanog mRNA, NANOG+ hepatocytes, and POU2F2+ NANOG+ hepatocytes at this time point, but it did not affect POU2F2+ hepatocytes production." (PMID 37733361, 2021). "During the four days following the infection, the CD44, SOX2, NANOG, and OCT4 levels have changed significantly at p ≤ 0.001 with respect to duration of infection." (PMID 33093503, 2020). "Compared to other CSC markers (OCT-3/4, NANOG, etc.), the percentage of cells positive for CD133 upon 11G5 infection might appear low." (PMID 38374654, 2024). "Our results showed that the infection did not change the mRNA expression of SOX2, NANOG, and POU5F1, but increased the mRNA expression of TLR4 and the cell surface expression." (PMID 40573358, 2025). "AAV8‐IL‐31, but not AAV8‐vector, infection also induced the development of POU2F2+ OCT4+, POU2F2+ SOX2+, and POU2F2+ NANOG+ hepatocytes at months 6 and 10 post‐DEN." (PMID 37733361, 2021).
adenocarcinoma (8 papers, 2010 to 2025). A common cancer characterized by the presence of malignant glandular cells. "The RT-PCR data from our patients revealed more SOX2 and NANOG expression in ALDHhigh cells than in ALDHlow cells in adenocarcinoma." (PMID 31921651, 2019). "Moreover, a previously characterized OCT4/SOX2/NANOG signature effectively separated lung SCCs from adenocarcinomas in two independent publicly available datasets which correlated with increased SOX2 mRNA in SCCs." (PMID 20161759, 2010). "Liu et al100 demonstrated that during the transition from adenocarcinoma to undifferentiated small-cell carcinoma, POU5F1, lin-28 homolog A (LIN28A), SOX2, and NANOG are sequentially activated, driving the transformation of differentiated adenocarcinoma to undifferentiated small-cell carcinoma." (PMID 40821114, 2025). "Expression heterogeneity was also found among LuCaP adenocarcinoma lines regarding the scTF genes – many with POU5F1, a few with LIN28A, none with SOX2 and NANOG." (PMID 31146720, 2019).
lip (4 papers, 2014 to 2023). "We also checked NANOG transcriptional level in human lung ADC cell lines from public database (EBML‐EBI expression atlas) and found that NANOG was expressed at an extremely low level with < 1 TPM/RPKM (Table EV1)." (PMID 33439550, 2021).
benign tumours (1 paper, 2022). "To investigate the clinical implications of NANOG and pAMPK in EOC, we performed IHC with TMAs from 212 EOCs, 52 borderline tumours, 83 benign tumours, and 70 nonadjacent normal epithelial tissues." (PMID 36114703, 2022).
NANOG also shares sentences with these, for which no sentence is quoted: brain cancer (4 papers); gastrointestinal tumors (4); choriocarcinoma (3); colon adenocarcinoma (3); hematological disorders (2); Huntington disease (2); metastasis (2); rheumatoid arthritis (2); adenoid cystic carcinoma (1); alcoholic cirrhosis (1); Alzheimer disease (1); amyotrophic lateral sclerosis (1); Azoospermia (1); B-cell neoplasm (1); carcinoma in situ (1); chronic hepatitis B (1); clear cell renal cell carcinomas (1); CNS germ cell tumors (1); Colon (1); colonic adenoma (1); combined immunodeficiency (1); COVID-19 (1); Duchenne muscular dystrophy (1); emphysema (1); germinoma (1); gonadoblastoma (1); heart malformations (1); hemangioblastoma (1); Hepatitis (1); Hyperglycemia (1).
A further 22 diseases each share a sentence with NANOG in 1 paper.